EZH2 (enhancer of zeste 2 polycomb repressive complex 2 subunit)
Diseases named in the same sentence as EZH2 in open-access papers (continued):
Sharing a sentence is not in itself a finding about the gene and the disease.
colon carcinoma (continued). "In contrast, no expression of EZH2 was observed in the non-aggressive colon cancer cells, which exhibit very little to nearly null PAR expression." (PMID 35955891, 2022). "Therefore, to further confirm the involvement of the EZH2-GLS axis in the adaptation to glucose deprivation, we performed immunofluorescence staining for EZH2 and GLS in larger colon cancer tissues." (PMID 34671029, 2021). "In colon cancer, lncRNA ROR1-AS1 can also bind to EZH2 and downregulate the expression of DUSP5." (PMID 33050646, 2020). "Subsequently, our present investigation revealed that LINC00152 was capable of facilitating EMT and resistance of EC cells to L-OHP via interacting with EZH2, which is partially corroborating previous results that LINC00152 facilitates EMT in colon cancer by interaction with β-catenin." (PMID 33292221, 2020). "A recent study in human colon cancer cells demonstrated that EZH2 alone, independent of H3K27me3, was sufficient to repress transcription." (PMID 29223978, 2018). "EZH2 is functionally considered to suppress miR-31 expression in human cancers; however, no study has reported its relationship with colon cancer." (PMID 26871294, 2016). "To evaluate whether there may be any correlation between EZH2 expression and LDM cytotoxicity, we compared the basal EZH2 protein expression in a panel of human colon cancer cell lines and IC50 of LDM." (PMID 27882937, 2016). "To assess the biological ramifications of EZH2 depletion on CRC cancer cells, we treated HT115, HT-29, and SW620 colon cancer cells with 3-deazaneplanocin A (DZNep), a small-molecule inhibitor known to target EZH2 protein, and assessed cell viability on days 4 and 8 posttreatment." (PMID 25611389, 2015). "Another study in colon cancer cells shows that EZH2 depletion results in G1/S arrest without p27 re-expression." (PMID 25431950, 2014). "For example, whereas EZH2 was consistently reported to be overexpressed in colon cancers, EZH2 expression levels correlated positively, negatively, or not at all, with the survival of colon cancer patients." (PMID 21765901, 2011). "IPA analysis of genes affected by EZH2 depletion in both DLD1 and LoVo colon cancer cells." (PMID 21765901, 2011). "In line with these in vivo findings, the basal levels of EZH2 protein expression did not consistently correlate with p27 protein or mRNA levels in colon cancer cell lines in vitro." (PMID 21765901, 2011). "We also investigated whether p27 expression levels are affected by EZH2 depletion in HCT116, LoVo, and DLD1 colon cancer cells." (PMID 21765901, 2011). "Morphological aspects, FACS profiles, and terminal deoxynucleotidyl transferase dUTP nick end labeling (TUNEL) analyses did not provide evidence for increased apoptosis of colon cancer cells upon RNAi-mediated EZH2 repression (data not shown)." (PMID 21765901, 2011). "A corresponding subgroup analysis within colon cancer stage III patients showed a trend for improved RFS with high EZH2 index (P=0.097), whereas a similar analysis for CSS was not significant (P=0.14)." (PMID 19773751, 2009). "We conclude that increased EZH2 protein expression and Ki-67 expression in >40% of the tumour cells are both associated with an improved RFS in colon cancer stages II and III, but not so in rectal cancer." (PMID 19773751, 2009). "Strong EZH2 expression and high proliferation are associated features and both indicate improved RFS in colon cancer, but not so in rectal cancer." (PMID 19773751, 2009). "Furthermore, in human colon cancer cells, ectopic deposition of H3K27me3 with an EZH2-dCas9 fusion construct was not sufficient for transcriptional repression." (PMID 29223978, 2018). "EZH2 has been shown to interact with PCNA-associated factor (PAF) to the β-catenin complex, and thereby promoting transcriptional activation of Wnt target genes, which is independent of methyltransferase activity of EZH2, in colon cancer cells." (PMID 28561778, 2017).
colon carcinoma (continued). "Moreover, to our knowledge, only one functional study investigated the role of EZH2 for the growth of colon cancer cells, but failed to see an effect upon EZH2 gene silencing." (PMID 21765901, 2011). "However, comparative analyses of EZH2 and p27 expression did not exhibit a statistically relevant positive or negative linkage in colon cancers in vivo, on a per patient basis." (PMID 21765901, 2011). "However, expression analyses of colon cancer cell lines and colon cancer biopsies did not reveal a consistent correlation between EZH2 and p27 levels." (PMID 21765901, 2011). "However, data comparing EZH2 expression in benign colon adenomas versus colon cancer is, to our knowledge, not yet available." (PMID 21765901, 2011). "Moreover, LPAR2 and LPAR5 mediate resistance of colon cancer cells to 5′-fluoro-uracil, whilst in the same tumour type, LPA enhances resistance to EZH2 inhibitors through LPAR2, suggesting that co-targeting of ATX/LPA/LPAR2 and EZH2 might be beneficial for colon cancer treatment." (PMID 38607068, 2024). "Furthermore, if EZH2T367D phospho-mimicking mutant is expressed in EZH2-depleted cells, target genes were expressed at significantly lower levels, even lower than in control cells—underscoring the importance of DCAF1-EZH2T367p for target gene inactivation in colon cancer cells." (PMID 37069142, 2023). "Moreover, EZH2 depletion did not re-induce p27 expression in colon cancer cells, indicating that p27 repression by EZH2 may be cell- or tissue-specific." (PMID 21765901, 2011). "Our findings revealed significant differences in both EZH2 and RUNX expression, while also confirming a significant negative correlation between their expressions in colon cancer tissues." (PMID 38048186, 2023). "Since Taz treatment alone did not appreciably alter EZH2 and EZH2T367p levels, these results support the dominant effect of B32B3 over Taz and point to DCAF1-mediated EZH2T367p as a key determinant for H3K27me3-induced oncogenic gene silencing in colon cancer." (PMID 37069142, 2023). "Moreover, another independent cohort of 162 colon cancer patients revealed a negative correlation between FXR and EZH2." (PMID 35449124, 2022). "Additionally, RT-qRCR and western blot assays revealed that EZH2 expression in CRC tissues and colon cancer cell lines HT-29, HCT-8, HCT116 was higher than that in normal adjacent tissues as well as colorectal epithelial cells FHC." (PMID 34288823, 2021). "Since CRISPR-Cas ko for EZH2 in HC116 cells was not successful (data not shown) in an attempt to mimic EZH2 status of CRC tumors at the invasion front, we treated HCT116 colon tumor cells with a common EZH2 inhibitor (DZNep) that is known to decrease the activity and protein level of EZH2." (PMID 31317325, 2019). "It has been hypothesized that miR-101 could restrain the migratory potential of cells by repressing the enhancer of zeste homolog 2 (EZH2); in fact, in vitro and in vivo studies showed how this peculiar miRNA is decreased in colon cancer tissues compared with adjacent non-tumor tissues." (PMID 32019170, 2020).
leukemia (116 papers, 2011 to 2025). A malignant (clonal) hematologic disorder, involving hematopoietic stem cells and characterized by the presence of primitive or atypical myeloid or lymphoid cells in the bone marrow and the blood. "Recurrent mutations in both EZH2 and DNMTs in leukemia suggest an underlying mutational synergy in epigenetic regulators that contributes to leukemogenic transcription." (PMID 40523422, 2025). "Leukemias harboring loss-of-function mutations in Polycomb-group epigenetic regulators, such as EZH2 and ASXL1, are associated with poor clinical outcomes and remain a major therapeutic challenge." (PMID 40561338, 2025). "EZH1, a homolog of EZH2, is essential for the initiation of leukemia in EZH2-deficient cells and contributes to epigenetic vulnerability." (PMID 40438606, 2025). "In mice, the loss of Ezh2 during leukemia induction leads to the resolution of a small number of ‘bivalent’ promoters, which harbor both repressive H3K27 trimethyl and activating H3K4 trimethyl marks." (PMID 40523422, 2025). "Activated BCAT1 cooperates with increased Glu to promote transamination of BCKA and maintain cellular BCAA pool levels, thereby affecting the development of EZH2-deficient leukemia." (PMID 36119495, 2022). "EZH2 has a bidirectional tumorigenic effect involving mTOR signaling, as shown in EZH2-deficient leukemia cells." (PMID 36686830, 2022). "NRasG12D and EZH2-deficiency-induced leukemia presents important features that recapitulate human AML with preceding preleukemic conditions, including the presence of an indolent MPN phase and the disease course over an extended period of time." (PMID 34732703, 2021). "In leukemias, in which mainly EZH2 loss-of-function occurs, it has recently been shown that EZH2 loss or reduced expression can cause the acquired drug resistance to TKI and cytotoxic drugs in AML as a result of HOX genes de-repression." (PMID 33917538, 2021). "Specifically, somatic EZH2 mutations have a major role in promoting lymphoid transformation in germinal-center leukemias." (PMID 34153035, 2021). "BCAT1 is generally low or not expressed in hematopoietic cells and exogenous expression of BCAT1 mimics the effects of the loss of EZH2 on leukemia initiating cells." (PMID 33329600, 2020). "BCAT1 reactivation along with NRASG12D mutations can sustain intracellular BCAA pools, resulting in enhanced mTOR signaling in EZH2-deficient leukemia cells." (PMID 32448308, 2020). "As EZH2 mutations are predominantly hemizygous, these data infer that the mutations occur as early events within the evolution of multiple leukemias, an observation that strongly corroborates our experimental data." (PMID 30890554, 2019). "Bulk-transduced populations were transplanted into recipient mice to generate primary murine leukemias and determine if coexpression of Plag1 or Lin28b would phenocopy Ezh2 loss and accelerate AML onset in comparison with MLL-AF9 alone." (PMID 30890554, 2019). "The reduced EZH2 expression in t-AML parallels reduced expression observed in primary AML or pre-leukemia, which was previously found in 78% of patients carrying either EZH2 inactive mutation or -7/del7q involving the EZH2 locus." (PMID 26043758, 2015). "Clinically, EZH2 mutations seem to commonly predict poor prognosis—worse OS/leukemia-free survival (LFS), high-risk IPSS score—especially in myeloid malignancies." (PMID 24622842, 2014). "Our investigation in the overall leukemia patient dataset reveals the most frequently observed EZH2 mutations to be R690 and D664, both of which are loss-of-function mutations; both are located in the SET domain (catalytic domain) and are directly associated with inactivation of PRC2." (PMID 40562788, 2025).
leukemia (continued). "However, at the second relapse, an additional mutation was detected in FLT3-TKD, which, along with EZH2, propagated overt leukemia." (PMID 40362463, 2025). "In hematologic malignancies, Branched-chain Amino Acid Transaminase 1 inhibitors have been found to effectively inhibit the proliferation of Enhancer Of Zeste Homolog 2-deficient leukemia-initiating cells (EZH2-deficient leukemia-initiating cells), both in vitro and in vivo." (PMID 39605897, 2024). "HOTAIR recruits EZH2 to the p15 promoter, inducing its H3K27me3 and silencing gene expression. p15 downregulation is associated with the enhanced self-renewal capacity of leukemia stem cells, promoting leukemogenesis." (PMID 37345170, 2023). "In addition, studies on EZH2-deficient leukaemia found that BCAT1 was abnormally activated in EZH2-deficient cancer-initiating cells." (PMID 36119495, 2022). "Here, we explored whether NRasG12D and EZH2-deficiency may act on independent pathways at the single-cell level to promote leukemia progression." (PMID 34732703, 2021). "Interestingly, shRNA-mediated inhibition of PRC2 subunit EED, SUZ12, or EZH1/EZH2 causes leukemia cells to stop proliferation and differentiation." (PMID 32436117, 2020). "These highlight an “epigenetic switch,” where loss of H3K27me3 is accompanied by an increase in H3K27Ac following Ezh2 loss and leukemia-initiating cells from the Ezh2−/−/Jak2V617F mice showed sensitivity to BET inhibitors, targeting gene expression related to altered H3K27Ac." (PMID 30890554, 2019). "However, previous research has also found that EZH2 overexpression is common and is associated with poor prognosis in solid cancers and leukemia." (PMID 26812882, 2016). "Notably, Leukemia 1 cells also over-express a number of chromatin regulators, including Brd3 and Polycomb complex members Ezh2 and Suz12, all of which have been linked with leukemia and other cancers." (PMID 25517911, 2014). "Therefore, in this patient, EZH2 was an early event associated with leukemia relapse." (PMID 40362463, 2025). "However, abnormal EZH2-associated regulation to particular target genes remains unclear in leukemia, specifically in t-AML." (PMID 26043758, 2015). "However, loss-of-function mutations in EZH2 indicate that it may also function as a TSG in leukemia." (PMID 25313314, 2014). "In this study, we explored the relative expression levels of key transcription factors in leukemia cells by RT-qPCR, and the results showed that E2F1 and EZH2 were significantly upregulated in leukemia cell lines compared with normal bone marrow stromal cells." (PMID 39498293, 2024). "More than 80% of patients with overt-PMF carry variants/mutations other than JAK2/CALR/MPL, in particular high-risk mutations which are associated with overall prognosis and leukemia-free survival (ASXL1, SRSF2, IDH1/IDH2, EZH2)." (PMID 36580136, 2023). "Low expression of EZH2 and H3K27me3 was also seen in about half of all samples of relapsed leukaemia in this cohort." (PMID 36980579, 2023). "Dual inhibition of DNMTs and EZH2 was also effective in prostate, breast, colon cancer and leukemia cells, highlighting the therapeutic potential of these interactions." (PMID 37664059, 2023). "We validated our microarray analysis by confirming the mRNA downregulation of two genes related to leukemia (EZH2 and JAK2), as well as the expression levels of 5 randomly selected proteins." (PMID 37801090, 2023). "As a comparison, knockout of Module #8 genes had minimal impact on cell fitness in K562 leukemia cell line that is EZH2 wildtype." (PMID 37460547, 2023). "Leukemia-free survival (LFS) and overall survival (OS) were significantly reduced in EZH2-mutated PMF patients." (PMID 35562964, 2022).
leukemia (continued). "In leukaemia, overexpression of EZH2 has been observed in CLL18, paediatric T-ALL19 and CML20, while other studies reported EZH2 levels to be decreased in CMML21 as well as ALL18,19,22." (PMID 33712646, 2021). "A recent publication showed that the activation of the JAK/STAT pathway leads to phosphorylation of enhancer of zeste 2 (EZH2) in a specific leukemia subtype." (PMID 34359703, 2021). "Of note, though, the numbers of ‘within state’ DEGs increased modestly in E2-KO and G12D/E2-KO HSPCs at late stages of leukemia development (T2 and T3), consistent with a direct role of EZH2 in regulating gene expression during leukemia progression." (PMID 34732703, 2021). "Suppression of EZH2 by DZNep has been shown to inhibit the formation of leukemia colonies and reduce H3K27me3." (PMID 34298959, 2021). "The effect of chidamide or EZH2-specific shRNA (shEZH2) in combination with adriamycin was studied in vivo in leukemia-bearing nude mouse models." (PMID 33743723, 2021). "To determine the combined effects of NRasG12D activation and EZH2-deficiency, we analyzed the myeloid differentiation pseudotime in all groups at T3 when post-MPN leukemia was observed in G12D/E2-KO mice." (PMID 34732703, 2021). "The impairmentof the EZH2–EED interaction led to proliferation arrest andmyeloid differentiation in PRC2-dependent MLL-AF9 leukemia cells andremarkably affected the viability of cancer cells bearing EZH2 mutantvariants." (PMID 34351144, 2021). "In this case, the therapeutic potential of targeting EZH2 has received considerable attention in leukemia/cancer management." (PMID 34093860, 2021). "Our work showed that targeting EZH2 can effectively suppress leukemia cell growth both in vitro and in vivo, but at the same time, we also notice that it has negative impacts on physiological functions such as normal hematopoiesis." (PMID 34093860, 2021). "Inhibition of EZH2 suppresses the level of H3K27me3, induces leukemia cell apoptosis and depletes LSCs." (PMID 33743723, 2021). "Here the authors analyze leukemia mouse models with both oncogenic NRAS and EZH2 mutations using single-cell RNA-sequencing, evaluate oncogenic cooperation, and identify GEM as a regulator of leukemia-initiating cells." (PMID 34732703, 2021). "In AML mouse models induced by the Mixed Lineage Leukemia (MLL)-AF9 translocation, EZH2 inactivation resulted in significantly reduced leukemia-initiating cells and enhanced differentiation." (PMID 32650416, 2020). "Several studies have provided evidence for the adverse impact of somatic mutations in ASXL1, EZH2, IDH1/2, and SRSF2 on shorter OS or leukemia-free survival in patients with PMF." (PMID 32781570, 2020). "Several NGS studies observed shorter OS or leukemia-free survival in MF patients with mutations in ASXL1, SRSF2, or EZH2." (PMID 32781570, 2020). "Analyses focused on CML cell lines, primary cells, as well as mouse models, suggest that combined TKI treatment and EZH2 inhibition can delay leukemia development, extend survival and decrease the LSC burden through upregulation of H3K27me3 targets." (PMID 32650416, 2020). "Interestingly, a study suggested that the loss of EZH2 could contribute to leukemia transformation." (PMID 31711520, 2019).